SEC61A2 (SEC61 translocon subunit alpha 2)
Description:
Component of SEC61 channel-forming translocon complex that mediates transport of signal peptide-containing precursor polypeptides across the endoplasmic reticulum (ER). Forms a ribosome receptor and a gated pore in the ER membrane, both functions required for cotranslational translocation of nascent polypeptides.
Synonyms: FLJ10578
Tractability: Antibody: UniProt predicts a signal peptide or a membrane-spanning region. PROTAC: ubiquitination databases record sites on it; its protein half-life has been measured.
Gene: Protein-coding gene on chromosome 10 (12,129,637 to 12,169,961, forward strand). Ensembl gene ENSG00000065665.
Subcellular location: Endoplasmic reticulum membrane
Pathways (Reactome):
Immune System: ER-Phagosome pathway
Metabolism of proteins: SRP-dependent cotranslational protein targeting to membrane
Gene Ontology:
Molecular function: protein binding; protein transmembrane transporter activity; ribosome binding; signal sequence binding
Biological process: post-translational protein targeting to membrane, translocation; SRP-dependent cotranslational protein targeting to membrane, translocation; protein transport
Cellular component: endoplasmic reticulum membrane; Sec61 translocon complex; membrane
Genetic constraint (gnomAD): Loss-of-function variants: 19 observed, 42.43 expected, observed/expected ratio (o/e) 0.45, 90% interval 0.31 to 0.66. The upper end of that interval is the gene's LOEUF score, 0.66, which puts it in group 2 of 6, group 1 being the genes least tolerant of losing a copy. Missense variants: 283 observed, 515.85 expected, observed/expected ratio (o/e) 0.55, 90% interval 0.5 to 0.61. Synonymous variants: 170 observed, 193.79 expected, observed/expected ratio (o/e) 0.88, 90% interval 0.77 to 1.
Homologues: Orthologues: chimpanzee SEC61A2 (100% identical), dog SEC61A2 (100% identical), mouse Sec61a2 (100% identical), rabbit SEC61A2 (100% identical), guinea pig SEC61A2 (99% identical), pig SEC61A2 (99% identical), Drosophila melanogaster Sec61alpha (91% identical), rat Sec61a2 (90% identical), Caenorhabditis elegans sec-61.A (87% identical). Paralogues in human: SEC61A1 (93% identical).
Diseases named in the same sentence as SEC61A2 in open-access papers:
SEC61A2 is named in the same sentence as 4 diseases in open-access papers, as found by Europe PMC text mining. Sharing a sentence is not in itself a finding about the gene and the disease. The quoted sentences say what the papers report.
ovarian carcinoma (2 papers, 2023 to 2025). A malignant neoplasm originating from the surface ovarian epithelium. "Our findings indicated that WEE1, PYHIN1, and SEC61A2 served as risk factors impacting the prognosis of ovarian cancer, while HAL demonstrated a protective effect." (PMID 37781709, 2023). "In ovarian cancer, BRCA1-mut cancer genes such as AIF1, CD8A, and BST1 showed detrimental prognosis, while in BRCA2-mut ovarian cancer, SEC61A2 and IGFBP3 were associated with shorter survival." (PMID 40647506, 2025). "Subsequently, to quantify the survival risk for each ovarian cancer patient, we developed a risk model utilizing a multi-factorial Cox formula based on the four aforementioned genes (WEE1, PYHIN1, SEC61A2, and HAL)." (PMID 37781709, 2023). "These include AIF1, CD8A, and BST1 in ovarian cancer BRCA1-mutant cancers, and SEC61A2 and IGFBP3 in BRCA2-mutant ovarian cancer." (PMID 40647506, 2025).
cancer (2 papers, 2023 to 2025). A tumor composed of atypical neoplastic, often pleomorphic cells that invade other tissues. "Our study suggests that monocyte-derived biomarkers, specifically WEE1, PYHIN1, SEC61A2, and HAL, hold potential as predictors for cancer prognosis and AMI." (PMID 37781709, 2023). "Most important of all, these findings demonstrate the potential of utilizing shared biomarkers (WEE1, PYHIN1, SEC61A2, and HAL) to predict outcomes in both cancer and AMI patients." (PMID 37781709, 2023). "However, further experimental studies are needed to elucidate the specific roles of WEE1, PYHIN1, SEC61A2, and HAL in disease occurrence, progression, and response to treatment in both cancer and AMI." (PMID 37781709, 2023). "In our study, our findings suggest that WEE1, PYHIN1, SEC61A2, and HAL derived from monocytes may serve as a potential predictor for AMI and cancer prognosis." (PMID 37781709, 2023). "In summary, our findings suggest that WEE1, PYHIN1, SEC61A2, and HAL derived from monocytes may serve as a potential predictor for AMI and cancer prognosis." (PMID 37781709, 2023).
tumor (1 paper, 2022). "SEC61A2 may be important for metastasis to the brain in humans when upregulated and finally SORBS2 has been reported to be a tumor suppressor gene in ccRCC." (PMID 35954157, 2022).
SEC61A2 also shares sentences with these, for which no sentence is quoted: Renal Cell Cancer (1 paper).